C4B (complement C4B (Chido/Rodgers blood group))
Description:
Precursor of non-enzymatic components of the classical, lectin and GZMK complement pathways, which consist in a cascade of proteins that leads to phagocytosis and breakdown of pathogens and signaling that strengthens the adaptive immune system. [Complement C4b-B]: Non-enzymatic component of C3 and C5 convertases (By similarity). Generated following cleavage by complement proteases (C1S, MASP2 or GZMK, depending on the complement pathway), it covalently attaches to the surface of pathogens, where it acts as an opsonin that marks the surface of antigens for removal (By similarity). It then recruits the serine protease complement C2b to form the C3 and C5 convertases, which cleave and activate C3 and C5, respectively, the next components of the complement pathways. Complement C4b-B isotype catalyzes the transacylation of the thioester carbonyl group to form ester bonds with carbohydrate antigens, while C4b-A isotype is responsible for effective binding to form amide bonds with immune aggregates or protein antigens. [C4a anaphylatoxin]: Putative humoral mediator released following cleavage by complement proteases (C1S, MASP2 or GZMK, depending on the complement pathway). While it is strongly similar to anaphylatoxins, its role is unclear. Was reported to act as a mediator of local inflammatory process; however these effects were probably due to contamination with C3a and/C5a anaphylatoxins in biological assays.
Synonyms: CO4; CPAMD3; C4F; C4B1; C4B3; CH; C4B12; C4B5; C4BD
Tractability: Antibody: UniProt places it where antibodies can reach, with high confidence; its Gene Ontology location is reachable by antibodies, with high confidence; UniProt predicts a signal peptide or a membrane-spanning region.
Gene: Protein-coding gene on chromosome 6 (32,014,730 to 32,035,973, forward strand). Ensembl gene ENSG00000224389.
Subcellular location: Secreted; Synapse; Cell projection, axon; Cell projection, dendrite; Secreted (C4a anaphylatoxin); Secreted (Complement C4b-B); Cell surface
Pathways (Reactome):
Immune System: Activation of C3 and C5; Initial triggering of complement; Regulation of Complement cascade
Disease: Dengue virus activates/modulates innate and adaptive immune responses
Gene Ontology:
Molecular function: carbohydrate binding; complement binding; endopeptidase inhibitor activity
Biological process: complement activation; detection of molecule of bacterial origin; positive regulation of apoptotic cell clearance; complement activation, GZMK pathway; opsonization; inflammatory response; response to other organism
Cellular component: blood microparticle; cell surface; extracellular exosome; extracellular region; symbiont cell surface; synapse; plasma membrane; axon; dendrite
Genetic constraint (gnomAD): Loss-of-function variants: 6 observed, 28.69 expected, observed/expected ratio (o/e) 0.21, 90% interval 0.11 to 0.41. The synonymous counts are far from expectation, so gnomAD's model fits this gene poorly and the ratio says little. Missense variants: 116 observed, 327.64 expected, observed/expected ratio (o/e) 0.35, 90% interval 0.3 to 0.41. Synonymous variants: 59 observed, 132.82 expected, observed/expected ratio (o/e) 0.44, 90% interval 0.36 to 0.55.
Homologues: Orthologues: chimpanzee C4A (98% identical), chimpanzee C4A (97% identical), pig C4A (81% identical), rat C4b (79% identical), mouse C4b (76% identical), mouse C4a (74% identical), tropical clawed frog c4a (39% identical), zebrafish c4 (33% identical), Caenorhabditis elegans tep-1 (17% identical), Drosophila melanogaster Tep2 (17% identical), Drosophila melanogaster Tep4 (17% identical), Drosophila melanogaster Tep3 (17% identical), and 1 more. Paralogues in human: C4A (99% identical), C3 (27% identical), C5 (24% identical), CPAMD8 (20% identical), A2M (20% identical), PZP (19% identical), A2ML1 (18% identical), CD109 (18% identical).
Diseases named in the same sentence as C4B in open-access papers:
C4B is named in the same sentence as 175 diseases in open-access papers, as found by Europe PMC text mining. Sharing a sentence is not in itself a finding about the gene and the disease. The quoted sentences say what the papers report.
schizophrenia (29 papers, 2016 to 2026). A major psychotic disorder characterized by abnormalities in the perception or expression of reality. "C4A, in contrast to C4B, is implicated in synaptic pruning and increased risk for schizophrenia, however beyond this their distinct roles within the human brain remain poorly understood." (PMID 42000733, 2026). "We directly genotyped 434 schizophrenia patients to determine their C4A and C4B copy number variants." (PMID 38341430, 2024). "For example, the schizophrenia risk gene complement component 4 (C4) has C4A and C4B isotypes in human, but solely C4b in mouse." (PMID 36474001, 2023). "Higher gene copy-number of C4A or a genetic deficiency of C4B, is a risk factor for neurologic or psychiatric disorder such as schizophrenia." (PMID 34764957, 2021). "We have genotyped the copy numbers of long and short forms of C4A and C4B gene variants in 129 European ancestry patients with schizophrenia or schizoaffective disorder." (PMID 31849639, 2019). "Particularly noteworthy is the finding that genetic polymorphisms of complement components C4A and C4B are significantly associated with various microbial environmental variables in schizophrenia patients, including a history of pathogen exposure and gut ecological imbalance." (PMID 41346597, 2025). "Similarly, exciting recent work identified copy number variations in the genes encoding complement component 4 (C4A and C4B) as the currently strongest risk factor for the development of schizophrenia." (PMID 39022733, 2024). "While genetic deficiency or depletion of C4A is associated with systemic autoimmune diseases, recent findings in neurologic disease suggested that high copy number of C4A or low copy number of C4B may be associated with schizophrenia." (PMID 34764957, 2021). "C4A and C4B, two isotypes of the human gene, are both upregulated in schizophrenia, with C4A expression higher than C4B." (PMID 35204837, 2022). "The role of C4B in autoimmune diseases and schizophrenia needs further studies, but low C4B copy number has been implicated in cardiovascular disease risk." (PMID 31849639, 2019). "As a result, varying levels of C4A and C4B expression in the brain are generated, implicating excessive complement activity in the development of schizophrenia that leads to the reduced numbers of synapses in the brains of individuals with schizophrenia." (PMID 31784692, 2019). "We also found the increased expression of component 4 (C4B) and C1QA and C1QB genes in male schizophrenia patients, which participate in inflammation and have been previously linked to schizophrenia vulnerability; meanwhile, increased C4 expression also prompts microglia-mediated engulfment in mice." (PMID 39068467, 2024). "Here, detailed genotyping of the most strongly associated GWAS locus in schizophrenia has revealed that copy numbers of the isogene C4A explains most of the risk, while C4B copy numbers do not increase schizophrenia risk." (PMID 36434058, 2023). "While multiple previous studies have confirmed the association between the C4A gene and an increased risk of schizophrenia, the intrinsic mechanism underlying the negative correlation between C4B and schizophrenia risk remains unclear." (PMID 41346597, 2025). "Among the ISGs exhibiting a DIU effect, complement factor 4 (C4B) is known as an essential component in the complement system and destroys foreign pathogens, and its copy-number variation has been reported to be associated with the risk of developing SLE, Sjogren’s syndrome, and schizophrenia." (PMID 39288763, 2024). "Considering that greater C4A expression in the brain is associated with increased schizophrenia risk, the C4b knockout mouse may not be a good model for schizophrenia and other microglia pruning-related disorders." (PMID 36474001, 2023). "We also probed the four complement genes located within the MHC region (i.e. C2, C4A, C4B and CFB) via schizophrenia PRS restricted to SNPs within each of them." (PMID 38649377, 2024).
schizophrenia (continued). "Biochemically, C4A and C4B differ at the site that determines what molecules they opsonize in tissues; genetically, the relative strengths of association of C4A and C4B (with NMO and schizophrenia) might reflect the encoded proteins’ differential binding to relevant sites in each tissue." (PMID 29769526, 2018). "The strongest genetic relationship for schizophrenia is with genetic markers located at the major histocompatibility complex (MHC) locus, which contains four genes that are related to the complement system (complement factor B, C2, C4A, and C4B)." (PMID 33670154, 2021). "We use PAQu to investigate differences in isoform abundance levels between people with schizophrenia and control subjects, confirming a long held hypothesis that levels of the C4A isoform of Complement Component 4 are increased in schizophrenia while C4B is not." (PMID 42079223, 2026).
lupus (18 papers, 2006 to 2025). "Early-onset SLE or lupus-like phenotypes have been associated with the deficiency of complement factors, including C1q, C1r, C1s, C2, C3, C4A, and C4B." (PMID 39660463, 2025). "Complete C4 complement deficiency involving both C4 isoforms (C4A and C4B) is rare and often presents as early onset of lupus-like illness." (PMID 38406130, 2024). "When either human C4A or C4B was expressed in a lupus-susceptible strain, mice expressing C4A developed less humoral autoimmunity than C4B-expressing mice." (PMID 35958588, 2022). "In addition, some studies have suggested an association of HLA-DR2, HLA-DR3, C4A, and C4B null complement alleles with drug-induced lupus." (PMID 36407159, 2022). "Lupus-like presentations have now been associated with inherited deficiencies in many classical pathway complement components, including C1q, C1r, C1s, C2, C3, C4A, and C4B." (PMID 29922296, 2018). "Although C4A and C4B share >99 % sequence identity, C4A has been suggested to have a primary role in immune complex clearance, greatly supported by the strong association between systemic lupus erythematosus (SLE) and low copy numbers of C4A." (PMID 27090374, 2016). "Lupus-prone families with primary defects of classical complement pathways (C1q, C1r/s, C2, C4A and C4B) revealed the importance of this pathway for lupus pathogenesis." (PMID 30744169, 2019). "Among these genes, the complement C4 gene with its isotypes C4A and C4B and the special feature of copy number variation has been repeatedly studied in lupus patients." (PMID 29050534, 2018). "In lupus, key mediators of tissue damage include C4b/C3b, C5a/C3a, and the MAC, all of which modulate membrane integrity or trigger inflammation in a setting where autoantibodies are already present in large amounts." (PMID 26913032, 2016). "C4B, which is upregulated in the brain from AD cases compared to controls in the ε2/ε3 group, was included in the light green network pathways involved in Staphylococcus aureus infection and systemic lupus erythematosus." (PMID 35139885, 2022). "In a longitudinal studies of pediatric lupus patients, it was found that patients with chronic hypertension persistently presented with higher serum protein levels of complement C4 and C3, and higher gene copy number of C4B." (PMID 34764957, 2021). "Third, in European family E94 with multiplex lupus-related mortality and low serum C4 levels, the culprit was a recurrent haplotype with HLA-A30, B18 and DR7 that segregated with two defective C4B genes and identical mutations at the donor splice site of intron-28." (PMID 34764957, 2021). "Genetic variants resulting in non-expression of complement C4A and C4B genes are common in healthy European populations and have shown association with a number of diseases, most notably the autoimmune disease, systemic lupus erythematosus." (PMID 21857912, 2011). "Thus, it probably makes sense to observe that W660x mutation in C4B was not detectable in subjects with systemic lupus erythematosus." (PMID 34764957, 2021). "We demonstrated the diversities of C4A and C4B proteins and their gene copy number variations (CNVs) in healthy subjects and patients with autoimmune disease, such as type 1 diabetes, systemic lupus erythematosus (SLE) and encephalitis." (PMID 34764957, 2021). "By KEGG pathway analysis, six genes, i.e., C4A, C4B, FCGR2A, HLA-DMA, HLA-DRA, and HLA-DRB1, were enriched as the top 2 significant results in the pathways of Staphylococcus aureus infection (KEGG term hsa05322, FDR = 1.42E−05) and systemic lupus erythematosus (KEGG term hsa05150, FDR = 2.00E−04)." (PMID 34804021, 2021). "Genetic variants resulting in non-expression of C4A and C4B genes (so-called “null” alleles, C4A*Q0 and C4B*Q0) are common in healthy European populations and have shown association with a number of diseases, most notably the autoimmune disease, systemic lupus erythematosus (SLE/lupus; MIM: 152700)." (PMID 21857912, 2011).
autoimmune disease (15 papers, 2006 to 2023). A disorder resulting from loss of function or tissue destruction of an organ or multiple organs, arising from humoral or cellular immune responses of the individual to their own tissue constituents. "Although there was increased incidence of symptoms detected post-infectiously reminiscent of autoimmune diseases (13.8% vs. 4.17% in C4B deficient patients and controls, respectively, OR = 3.68, 95% CI = 1.25–10.87, p = 0.013)." (PMID 29928053, 2018). "Accordingly, homozygous deficiency of C4A has been reported to associate with increased frequency of autoimmune diseases, whereas homozygous C4B deficiency has been associated with increased susceptibility of bacterial and enveloped viral infections." (PMID 29928053, 2018). "First, heterogeneity among ethnic groups or disease types was discovered when the association between C4, C4A, and C4B CNVs and autoimmune diseases was investigated." (PMID 28205620, 2017). "Although several studies have investigated the association between C4, C4A, and C4B gene copy number variations (CNVs) and susceptibility to autoimmune diseases, the results remain inconsistency for those diseases." (PMID 28205620, 2017). "While a complete deficiency of C4 is rare, an isotype deficiency of either C4A or C4B is much more commonly observed and has been implicated in several autoimmune diseases." (PMID 26913032, 2016). "Accordingly, phenotypic C4A deficiencies have been traditionally associated with susceptibility to autoimmune diseases, whereas C4B deficiencies have shown predisposition to infections with encapsulated bacteria, acute myocardial infarction and stroke." (PMID 22737222, 2012). "Among known classical complement receptors (CR), only type 1 complement receptor (CR1/CD35) was shown to bind both C4b and C3b fragments of cleaved C4 and C3 using two different domains for C4b and C3b, and this receptor is associated with the pathogenesis of certain autoimmune diseases." (PMID 37234916, 2023). "On the other hand, in humans, low levels, or deficiency in C4B expression were associated with a high risk of SZ, autism spectrum disorders (ASD), and certain autoimmune diseases." (PMID 37234916, 2023). "Recent studies have reported that diversities of C4A and C4B proteins and their gene copy number variations (CNVs) in healthy subjects and patients with autoimmune diseases." (PMID 36420131, 2022). "Some limitations of the current meta-analysis of the potential relationship between C4, C4A, and C4B CNVs and autoimmune diseases need to be addressed." (PMID 28205620, 2017). "Additionally, it has been reported that C4A and C4B copy number variations are related to autoimmune disorders." (PMID 32878183, 2020). "Thus, in this study, a comprehensive meta-analysis was conducted to assess the role of C4, C4A, and C4B CNVs in autoimmune diseases in different ethnic groups." (PMID 28205620, 2017). "Despite of the fact that the origin of autoimmunity in autism is unknown, immune related genes on major histocompatibility complex, which have been associated with some autoimmune diseases, may play a central role in the development of autoimmunity in autism (e.g., HLA-DRB1 and C4B null alleles)." (PMID 21513576, 2011). "Additionally, the correlation between C4B CNVs and all type of autoimmune diseases could not be confirmed by the current meta-analysis (OR = 1.07, 95% CI = 0.93–1.24)." (PMID 28205620, 2017).
COVID-19 (10 papers, 2021 to 2025). A disease caused by infection with severe acute respiratory syndrome coronavirus 2. "Whilst all patient sera in our study were positive for antibodies against K. pneumoniae, both SBA and complement opsonisation of K. pneumoniae (including deposition of C3b, C4b, and C5b-9) were compromised in sera of acute COVID-19 patients due to a loss of complement functional activity." (PMID 35572551, 2022). "Children with convalescent COVID-19 had significantly elevated levels of C1q, C2, C3, C3b/iC3b, C4b, C5, C5a, and MBL complement proteins and of complement regulatory proteins like factor B and factor H in comparison with children in the control group." (PMID 36961465, 2023). "Children with acute COVID-19 also had significantly elevated levels of C1q, C2, C4, C3, C5, C3b/iC3b, C4b, C5a, and MBL complement proteins and of complement regulatory proteins like factor B, factor D, factor H, and factor I in comparison with control children (eTable 2 in Supplement 1)." (PMID 36961465, 2023). "Upregulation of C1s (1.60-fold), C1q (1.53-fold), C2 (2.76-fold), C3 (1.9-fold), and C4b (2.45-fold) indicated that timely complement activation may contribute to COVID-19 in CMs." (PMID 35903092, 2022). "Having shown that serum from patients with acute severe COVID-19 is compromised in its ability to opsonise K. pneumoniae with complement C3b and C4b, we tested whether the bactericidal activity of the serum was similarly affected." (PMID 35572551, 2022). "The increased deposition of MBL, MASP-2, C3b, C4b, and C5b-9 on endothelial cells in COVID-19 patients is similar to the pathophysiology demonstrated in aHUS, which may serve to explain COVID-19’s potential triggering function of aHUS." (PMID 34944087, 2021). "In our proteomic analysis, C4b (C4b-binding protein beta chain) and coagulation factor VIII were upregulated in COVID-19 patients." (PMID 35937696, 2022). "The complement proteins C1q, C2, C4, C4b, MBL, C5, C5a, C3, C3b and complement factors such as factor B, factor D, factor H, and factor I were significantly enhanced in children with severe or moderate COVID-19 (eFigure 3, eTable 5, eTable 6 in Supplement 1)." (PMID 36961465, 2023). "Also, in lung tissue from patients with non-resolvable COVID-19 (long COVID), elevated mRNA expression of MASP-2 and associated complement factors (C4a/C4b) suggests sustained lectin and classical pathway activity contributing to progressive fibrosis." (PMID 40869200, 2025). "Therefore, we compared the admission (pretreatment) plasma levels of C1q, C2, C4, C4b, MBL, C5, C5a, C3, C3b, factor B, factor D, factor H, and factor I between children with COVID-19 who developed moderate or severe disease and those who developed only mild disease." (PMID 36961465, 2023).